HNMT (histamine N-methyltransferase)
Description:
Inactivates histamine by N-methylation. Plays an important role in degrading histamine and in regulating the airway response to histamine.
Synonyms: HMT; HNMT-S1; HNMT-S2; MRT51
Tractability: Small molecule: a structure with a bound ligand is known; it has a high-quality binding pocket; it belongs to a druggable protein family. PROTAC: ubiquitination databases record sites on it; its protein half-life has been measured; a small molecule that binds it is known.
Target class: Enzyme; Transferase
Safety:
Unwanted effects reported when the protein is acted on. In parentheses: how it was acted on, where the effect was seen, and who reports it.
acetylsalicylic acid-intolerant chronic urticaria (source: ClinPGx)
cardiotoxicity (source: ClinPGx)
Gene: Protein-coding gene on chromosome 2 (137,964,020 to 138,016,364, forward strand). Ensembl gene ENSG00000150540.
Subcellular location: Cytoplasm
Subcellular location (Human Protein Atlas): Cytosol; Nucleoplasm; Centrosome
Pathways (Reactome):
Metabolism: Histidine catabolism; Metabolism of ingested SeMet, Sec, MeSec into H2Se
Gene Ontology:
Molecular function: histamine N-methyltransferase activity; methyltransferase activity; N-methyltransferase activity; selenol Se-methyltransferase activity
Biological process: histamine catabolic process; histamine metabolic process; methylation; L-histidine catabolic process; respiratory gaseous exchange by respiratory system; selenium compound metabolic process
Cellular component: cytoplasm; cytosol; extracellular exosome
Genetic constraint (gnomAD): Loss-of-function variants: 13 observed, 13.06 expected, observed/expected ratio (o/e) 1, 90% interval 0.65 to 1.57. The upper end of that interval is the gene's LOEUF score, 1.57, which puts it in group 6 of 6, group 1 being the genes least tolerant of losing a copy. Missense variants: 162 observed, 195.87 expected, observed/expected ratio (o/e) 0.83, 90% interval 0.73 to 0.94. Synonymous variants: 61 observed, 68.71 expected, observed/expected ratio (o/e) 0.89, 90% interval 0.72 to 1.1.
Homologues: Orthologues: chimpanzee HNMT (99% identical), macaque HNMT (92% identical), dog HNMT (88% identical), rabbit HNMT (88% identical), pig HNMT (87% identical), rat Hnmt (84% identical), mouse Hnmt (84% identical), guinea pig HNMT (82% identical), tropical clawed frog hnmt (55% identical), zebrafish hnmt (44% identical).